CTNNB1 (catenin beta 1)
Diseases named in the same sentence as CTNNB1 in open-access papers (continued):
Sharing a sentence is not in itself a finding about the gene and the disease.
tumor (continued). "Four missense variants were heterozygous in the tumor sample and not present in blood (FAM117B, CTNNB1, CELSR3 and STXBP5L)." (PMID 33379206, 2020). "Protein expression of genes CCND1 and c-myc which are downstream of CTNNB1 in the WNT-pathway could be demonstrated as well, but protein expression was relatively weak as expected for a benign tumor." (PMID 32155193, 2020). "In the absence of a well-defined, mammary-specific WNT/CTNNB1 target gene expression program and given the preponderance of paraffin embedded tumor specimens, immunohistochemical detection of CTNNB1 protein levels has been used as the most direct way to readout WNT/CTNNB1 signaling." (PMID 32083079, 2020). "In consistence with our previous findings, the results showed that ATP6AP2 expression is higher in tumor tissues than that in normal tissues, moreover, level of ATP6AP2 transcripts in COAD is positively correlated with those of LRP6, CTNNB1, MYC, CCND1 and AXIN2." (PMID 32143717, 2020). "We then quantified the expression of DNER, RBPJ, SKP1, CTNNB1, and CDH2 in solid tumor and paratumor paraffin sections by immunohistochemistry and found strong cytoplasmic positivity of DNER in tumor tissue compared with paratumor tissue, with significant differences (P < 0.05)." (PMID 33329729, 2020). "Apart from PTEN, there were other genes which mutated at a lower percentage in our series, such as CKIT or CTNNB1 (both mutated at less than 1% and only in non-oropharyngeal HPV-negative tumours), have been reported in HNSCC in varied percentages." (PMID 33024167, 2020). "Additionally, the crosstalk between the WNT/CTNNB1 and PI3K/AKT signaling has been reported in the development and progression of tumor." (PMID 31511060, 2019). "Indeed, several genes such as CTNNB1, CCND1 and NKD1 involved in the Wnt/β-catenin signaling pathway showed increased m6A methylation in tumor tissues with respect to normal." (PMID 31870368, 2019). "We identified seven oncogenes (NRAS, EGFR, RXRA, HRAS, KRAS, AKT1, ERBB2; q<0.10) and seven putative tumor suppressor genes (ARID1A, TXNIP, CTNNB1, PIK3RI, CDKN2A, KLF5, STAG2; q<0.10) significantly regulated between tumor and control, which were formerly reported to be altered in BC." (PMID 30419021, 2018). "We studied a retrospective cohort of 160 consecutive surgically treated NSCLC patients with available frozen tumor samples for expression of EMT markers (CDH1, CTNNB1, CDH2, and VIMENTIN), inducers (TGFB1, c‐MET, and CAIX), and transcription factors (EMT‐TF:SNAI1, SNAI2, ZEB1, TWIST1, and TWIST2)." (PMID 29845746, 2018). "While in early-stage SCC patients, SOX30 has no role on tumor-metastasis and Wnt/CTNNB1-signaling duo to not binding to CTNNB1 promoter and results in an unfavorable prognosis of the patients." (PMID 30514297, 2018). "Circulating copies of CTNNB1 mutants (ctDNA) were detected in the plasma of 6 patients (33%) but their concentration was not correlated with evolution of the tumor." (PMID 29719606, 2018). "Patients with low circulating miR-193b had mainly alpha-fetoprotein (AFP) negative tumours, in line with previous reports of observed lower levels of AFP in CTNNB1-mutated HCC41." (PMID 27618837, 2017). "The Spearman analysis showed that CDH1, CTNNB1 were significantly relevant with tumour sizes (p = 0.03) and clinical stage (p < 0.001) not age (p = 0.461), gender (p = 0.335), smoking (p = 0.224)." (PMID 29115924, 2017).
tumor (continued). "MMR-deficient and CTNNB1-mutant were considered at intermediate risk, while POLE-mutant tumours and tumours with no specific molecular profile are designated favourable." (PMID 28424422, 2017). "These tumors form without a polypoid intermediary and also lack nuclear CTNNB1 (β-catenin), indicating a non-canonical mechanism of tumor initiation mediated by the PI3K pathway." (PMID 26863299, 2016). "It down-regulates CTNNB1-mediated transcriptional activation of target genes, such as CCND1 and may thereby act as a tumour suppressor." (PMID 27429002, 2016). "In this challenging case, the diagnosis of a β-catenin-activated HCA is favored, but the lack of molecular evidence for CTNNB1 alterations suggests alternative mechanisms of β-catenin activation and GS overexpression in the tumor." (PMID 26961851, 2016). "The tumours from which the cell lines were derived have been assigned to MB molecular subtypes using IHC for β-catenin, Gli1, NPR3 and KCNA1, and sequencing of the β-catenin gene (CTNNB1)." (PMID 24887326, 2014). "The results of the differential expression analysis of the pre- and post-therapeutic tumour specimen also suggests that the impact of GSK3B and CTNNB1 to this signature is not dependent on chemotherapy but rather related to a property of the primary tumour." (PMID 22970250, 2012). "The comparison of GSK3B and CTNNB1 expression levels between pre- and post-therapeutic tumour samples revealed no clear differences, whereas a significant increase in the expression of NOTCH2 was found." (PMID 22970250, 2012). "Copy number data generated from Affymetrix SNP chip (Affymetrix, Santa Clara, CA, USA) analysis for 12 of the CNS PNETs used in this study (six nuclear and six cytoplasmic CTNNB1) suggest that this is not the case for this tumour type." (PMID 19293793, 2009). "CCND1 was also overexpressed in 1 out of 27 (4%) tumours with cytoplasmic or negative CTNNB1 staining." (PMID 19293793, 2009). "A total of 4 out of 17 (24%) tumour samples displaying cytoplasmic or negative CTNNB1 staining also overexpressed CCND1." (PMID 19293793, 2009). "Correlation of CCND1 overexpression and CTNNB1 nuclear localisation was not absolute in either cohort, with some tumours displaying only cytoplasmic or negative CTNNB1 staining overexpressing CCND1." (PMID 19293793, 2009). "Tumours from 464 of 656 patients, which did not harbour a truncating APC mutation or lacked hMLH1 expression, were analysed for mutations in exon 3 of the CTNNB1 gene." (PMID 16356174, 2005). "When the diagnosis is restricted to neoplasms with typical features, the vast majority of primary Sertoli cell tumour NOS (>90%) show evidence of Wnt pathway activation, mostly, albeit not exclusively, by gain‐of‐function CTNNB1 exon 3 variants." (PMID 41384702, 2026). "Eliminating or reducing the activity of HUWE1 itself, which in turn reduces WNT/CTNNB1 signaling in WT HAP1-7TGP, CSNK1A1KO and CTNNB1ST-A cells, is unlikely to be a viable therapeutic strategy due to the multiple roles of HUWE1 on cell physiology, including tumor suppressor functions." (PMID 40424469, 2025). "The combination therapy primarily enhances anti-tumor activity by inhibiting the Wnt/β-catenin/CBP/c-myc signal, β-catenin nuclear translocation, and the AKT/p-AKT and ERK/p-ERK signaling pathways, independent of CTNNB1 mutation." (PMID 40593458, 2025). "The single CTNNB1-mutant tumor (Patient 5) showed no copy number alterations." (PMID 40906279, 2025).
tumor (continued). "In summary, combination therapy primarily enhances anti-tumor activity by inhibiting the Wnt/β-catenin/CBP/c-myc signal, β-catenin nuclear translocation, and the AKT/p-AKT and ERK/p-ERK signaling pathways, independent of CTNNB1 mutation." (PMID 40593458, 2025). "In younger patients, enrichment of CTNNB1 and RNF43 mutations suggests that non-canonical WNT activation may contribute more prominently to EOCRC, potentially driving more aggressive tumor biology and earlier onset of disease." (PMID 40940930, 2025). "Eliminating or reducing the activity of HUWE1 itself, which reduces WNT/CTNNB1 signaling in WT HAP1–7TGP, CSNK1A1KO and CTNNB1ST-A cells, is unlikely to be a viable therapeutic strategy due to the pleiotropic effects of HUWE1 on cell physiology, including tumor suppressor functions." (PMID 38410441, 2024). "Interestingly, the most upregulated gene in low UMIS tumor cells was the long non-coding RNA, SNHG7, which was 3.48-fold upregulated in low UMIS tumor cells (log2(fold change) = −1.80, FDR ~ 0) and has been previously reported as a positive regulator of CTNNB1 expression in several cancers 34–38." (PMID 38627362, 2024). "At the time of resection, tumor samples were sent for PCR testing of the CTNNB1 gene, which was not identified; however, it is noted that this testing was confined to exon 3 (codons 41 and 45), which includes the hotspot mutations typically seen in desmoid fibromatosis tumors only." (PMID 39597961, 2024). "Notably, all sequenced DIAMOND tumours show a consistent upregulation of Ctnnb1 and Lef1, while Tcf7l2 is not differentially regulated." (PMID 37907668, 2023). "Expression levels of CTNNB1 (β-catenin) and SOX9, which is a transcriptional target of the β-catenin transcription factor complex, were plotted together with γδ T-cell density values determined by IHC from the same, matched tumor samples from the Scotland cohort." (PMID 37309673, 2023). "Also, HHUA-SP-derived tumors expressed more CTNNB1 as compared to HHUA-MP-derived tumors, suggesting that enhanced tumor formation by HHUA-SP might be attributable to a higher self-renewal capacity of HHUA-SP." (PMID 35659728, 2022). "CTNNB1 and APC mutations are mutually exclusive with no neoplasm exhibiting a mutation in both." (PMID 36428715, 2022). "Activated CTNNB1, through signalling events initiated by phosphorylation of AKT, translocates to the nucleus and initiates the expression of downstream targets such as CCND1 and CCNE, TWIST, SNAIL, MMPs, C-MYC, and several others rendering tumor cells more invasive." (PMID 33758996, 2022). "However, some pathways, such as those related to immune depletion or the promotion of tumor growth, were significantly up-regulated in patients with CTNNB1-MUT, perhaps explaining why HCC patients with CTNNB1-MUT have a significantly worse immunotherapy prognosis." (PMID 34777372, 2021). "However, we have not found the relationship between CTNNB1: rs1880481 and the three serum tumor biomarkers, indicating that a multi-center study and sufficient clinical data are necessary to verify the results." (PMID 32453708, 2020). "In one tumor, with ALK positive reaction, negative nuclear reaction against β-catenin and the lack of CTNNB1 mutation, next generation sequencing revealed a presence of pathogenic variant c.3366_3369del in the APC gene, with homozygous deletion leading to inactivation of both copies in tumor cells." (PMID 30523493, 2019).
tumor (continued). "Four of the five upregulated RMGs (CTNNB1, EGFR, NRAS, and KIT) were oncogenes and 12 of the 32 downregulated RMGs were tumor suppressor genes, which was consistent with the increased expression of oncogenes and decreased expression of tumor suppressor genes in tumor development." (PMID 30107644, 2018). "However, in early-stage SCC patients, SOX30 has no inhibitory role on tumor-metastasis due to not binding to CTNNB1 promoter leading to an unfavorable prognosis of the patients." (PMID 30514297, 2018). "Some of these proteins are key components of cell-cell or cell-matrix adhesion and includes annexin and integrins such as ANXA1, ANAX2, ITGB1, ITGA3, FN1, CTNNB1, APOH which interplay may activate exosome and leukocyte adhesion to tumor cells to limit tumor growth." (PMID 30111323, 2018). "We identified a group of CTNNB1/TCF target genes that are activated in the absence of TCF7L1, including EPHB3, a marker of Paneth cell differentiation that has also been implicated as a tumor suppressor in CRC." (PMID 27333864, 2016). "Interestingly, one patient (HCC32) had a tumor-associated mutation of HCC (c.122C>T, CTNNB1) in plasma DNA but not in the primary tumor DNA." (PMID 27248174, 2016). "One could argue that these tumours are in effect the same as the WT1-mutant tumours, having no functional WT1 protein in combination with a CTNNB1 mutation." (PMID 26035382, 2015). "Furthermore, despite β-catenin activation observed in an additional subset of non-CTNNB1 mutated HCC, which showed high LECT2 expression, serum LECT2 levels were not predictive for active β-catenin signaling in the tumor." (PMID 24892551, 2014). "To corroborate the role of EZH2 and CTNNB1 in miR-214-mediated tumor cell invasion, we rescued the expression of EZH2 and CTNNB1 in miR-214 stable transfected HLE cells by transfecting a plasmid carrying wild-type EZH2 (pLVTHM-EZH2) or CTNNB1 (pCI-CTNNB1, Addgene)." (PMID 22962603, 2012). "No deletions in exon 3 of CTNNB1 were detected in our sample group, but this may be an under-estimation as we were unable to amplify the gene fragment in 6% of our tumours." (PMID 21992464, 2011). "To further exclude the possibility of pathological misclassification of endometrioid, clear cell or LGS tumours in the mutation-negative cases, we also tested for mutations commonly associated with these subtypes in KRAS (exon 2), BRAF (exon 15), CTNNB1 (exon 3), and PIK3CA (exons 10 and 21)." (PMID 20229506, 2010). "However, only one mutation was found in 32 tumours sequenced, which included 17 tumours with no IHC result, and therefore no known WNT/β-catenin pathway status, suggesting CTNNB1 exon 3 mutation to be rare." (PMID 19293793, 2009). "A total of 60% of CTNNB1 nuclear cases were desmoplastic compared with 31% of non-nuclear tumours." (PMID 19293793, 2009). "Six additional primary and two recurrent tumours with CTNNB1 nuclear staining were not sequenced." (PMID 19293793, 2009). "However, the significant correlation with CTNNB1 nuclear localisation found particularly in the CNS PNET cohort, strongly suggests that the WNT/β-catenin pathway is increasing CCND1 expression in the tumours with pathway activation in this study." (PMID 19293793, 2009). "Conversely, in tumours lacking these APC mutations, activating missense mutations at one of the phosphorylation sites at codons 31, 33, 37 and 45 of exon 3 of the CTNNB1 gene (encoding the β-catenin protein) can render it stable as it can no longer be tagged for cellular degradation." (PMID 16356174, 2005). "In Ctnnb‐1 mutated HCC model, the absence of LECT2 in tumour hepatocytes contributed to the EMT (epithelial to mesenchymal transition) of cancer cells and the recruitment of immature inflammatory monocytes that possessed immunosuppressive properties and tumour‐promoting potential." (PMID 35656863, 2022).
tumor (continued). "In addition to CTNNB1, our ctDNA profiling results did not indicate an association of any specific mutation with treatment response and PFS, suggesting that the tumor mutation profile might not affect the efficacy of Atezo/Bev therapy." (PMID 35884434, 2022). "In addition, CTNNB1 can act as a signal transduction molecule and its activation significantly stimulates the production of VEGF, upregulates the expression of MMPs to enhance the degradation of extracellular matrix (ECM), and thus promotes tumor cell growth, invasion and metastasis." (PMID 34465343, 2021). "As cultured tumor cells have two copies of chromosome 3 (data not shown) and UPD of 3p this indicates that the homozygous p.S45Δ mutation in the cell culture is the result of a mitotic recombination with loss of the normal CTNNB1 allele and duplication of the mutant allele." (PMID 27213811, 2016). "We show that the impact of GSK3B and CTNNB1 to this signature is not dependent on chemotherapy and more likely reflects a property of the primary tumour and our data further suggest, that in particular NOTCH2 might play a role for chemotherapy resistance in GC." (PMID 22970250, 2012). "However, comparison of high CTNNB1 nuclear cases to all other tumours (low CTNNB1 nuclear plus cytoplasmic and negative cases), although not significant (overall survival, P=0.113), suggested a trend towards the association of high CTNNB1 nuclear staining with a more favourable outcome." (PMID 19293793, 2009). "However, 70% of tumours with nuclear localisation of CTNNB1 did not display CCND1 overexpression." (PMID 19293793, 2009). "High nuclear Ctnnb1 staining was also observed in infrequent, undifferentiated, Apcfl/fl;R26LSL-MYC end-stage tumours unlike the Ctnnb1ex3/WT;R26LSL-MYC tumours that maintained lower levels of nuclear Ctnnb1." (PMID 41261129, 2026). "The tumours that arose in this genetic background had low WNT pathway activation, did not express nuclear Ctnnb1 and GLUL, and expressed IGFBP2 at variable levels." (PMID 41261129, 2026). "However, while we observed a direct association between CTNNB1 and CD3+ immune cells, LEF-1 was not linked to any of the immune cell subtypes but interestingly associated with impaired expression of antigen presentation in tumours suggesting modulation of immune recognition." (PMID 40130164, 2025). "To date, the literature supports the tumor suppressor functions of DAG1, SLC39A8, TMEM173/STING1, TJP1, CTNNB1, and SMC3, but not RDX." (PMID 36499305, 2022). "Interestingly an increased level of nuclear β-catenin in ovarian cancer is correlated with a favorable patient prognosis, so the growth-suppressing function of WNT5a in this tumor type may not stem from the inhibition of CTNNB1 signaling, but from the regulation via non-canonical WNT signaling." (PMID 36612190, 2022). "In contrast, the switches in the tumor drivers CDKN2C and CTNNB1, the former in LUSC and LUAD and the latter in LUSC, do not affect the protein." (PMID 25578962, 2015). "We show here that the coactivation of LIN28A overexpression and stabilized CTNNB1 in neural precursor cells during embryonic development, defined as the GBL model, was not sufficient to drive tumor formation during the examined time frame of embryonal development." (PMID 40680886, 2025).